CAT (catalase)
Diseases named in the same sentence as CAT in open-access papers (continued):
Sharing a sentence is not in itself a finding about the gene and the disease.
Sepsis (continued). "In 44 newborns with sepsis, MDA, SOD, GPx, and CAT were significantly increased in comparison to controls, while uric acid and albumin levels were significantly reduced, and similar changes were also observed in those newborns who died because of sepsis in comparison to survivors." (PMID 30174784, 2018). "The different modulation of SOD and CAT during sepsis may rise from some reasons below." (PMID 29230271, 2017). "Due to its good biocompatibility and excellent turnover rate, catalase-based EMNMs are widely used in environments with H2O2, such as tumors and sepsis sites." (PMID 39896991, 2025). "During the reaction of the EMNMs, the PCT of a blood sample from sepsis patients would bind to the anti-PCT of the nanoparticles and it was then bound with catalase to form catalase-based EMNMs via immunoassay." (PMID 39896991, 2025). "In our study, both protective and therapeutic effects of ozone treatment on sepsis were demonstrated, characterized by decreased TBARS and GST levels and increased catalase levels." (PMID 39336593, 2024). "During the onset of sepsis, the enzyme activities of SOD and CAT were significantly decreased, but BRD3308 restored the activity of these enzymes." (PMID 39224841, 2024). "The antioxidant system, encompassing elements like catalase (CAT) and glutathione (GSH), endeavors to neutralize the damaging ROS but often gets overwhelmed in the process of sepsis, aggravating tissue damage and propelling the inflammatory response." (PMID 38326366, 2024). "The ovarian activities of SOD (69% and 37%, respectively), CAT (60% and 34%, respectively) enzymes, and the level of GSH (79% and 47%, respectively) were significantly lower in sepsis according to NR-treated group." (PMID 36648023, 2023). "Exercise training appeared to normalize antioxidant protein expression in the setting of sepsis (G1 vs. G4 vs. G6) of SOD1, SOD3, and CAT." (PMID 37407986, 2023). "In this study, the activity of CAT and SOD in organs and serum of moderate and severe sepsis animals decreased significantly, and the content of oxidation reaction product 8-iso-PGF2α increased significantly." (PMID 36836478, 2023). "Zingerone also lowered the plasma levels of IL-6 and TNF-α, reduced lethality due to CLP-induced sepsis, raised lipid peroxidation, and improved the antioxidant defence system by restoring the concentrations of SOD, GPX, and CAT in kidney tissues." (PMID 36588685, 2022). "Compared with those in the sepsis group, the levels of IL-6, IL-1β and TNF-α were increased (P < 0.05), the MDA content was increased, while the SOD and CAT activities were decreased in the sepsis + BAY 87–2243 group (P < 0.05)." (PMID 35576220, 2022). "In LPS-mediated sepsis rats, the contents of antioxidant enzymes SOD, CAT and GR all have abnormally decreased, and MDA has increased, indicating that oxidative stress damage occurred during sepsis." (PMID 35148668, 2022). "Compared with those in the sham group, the levels of IL-6, IL-1β and TNF-α in the sepsis group were increased (P < 0.05), the MDA content was increased, and the SOD and CAT activities were decreased (P < 0.05)." (PMID 35576220, 2022). "In sepsis, elevated superoxide dismutase (SOD)/catalase (CAT) ratio and the accumulation of H2O2 in the cell, decreased glutathione levels, and enhanced protein carbonyl groups and malondialdehyde levels occur." (PMID 35706715, 2022). "The results showed that bFGF-RBC/NP significantly enhanced the antioxidant GSH level and activities of fundamental antioxidant enzymes, including GPX, CAT, and SOD, in the heart during sepsis-cardiac injury." (PMID 35656291, 2022).
Sepsis (continued). "Our results suggest that PEGylated catalase can effectively regulate cytokine production by activated leukocytes, suppress the elevated level of AST, ALT, TNF-α, and IL-6 in mice with induced sepsis, and significantly improve the survival rate of the mice." (PMID 34888304, 2021). "Herein, MLT increased the levels of GPx, CAT, and SOD in the heart tissues from the sepsis-affected mice." (PMID 34708067, 2021). "From the analysis of GSH, SOD, CAT, MAD, and ROS, it is clear that redox imbalance occurs in the kidney during sepsis." (PMID 32158395, 2020). "Although these results are different from our present data, further evidences of catalase inhibition by phlorizin suggested that the reasons for this discrepancy of the salbutamol treatment may be due to the different dose, route of administration, and period of observation after sepsis induction." (PMID 31536570, 2019). "On the other hand, the activities of SOD, CAT, and GSH were significantly decreased in mice with CLP-induced sepsis." (PMID 30154452, 2018). "The redox imbalance in LPS-induced sepsis resulting from depletion of glutathione (GSH) and catalase (CAT) levels and increase in malondialdehyde (MDA) levels was also found to have been reversed by COS exposure." (PMID 25594943, 2015). "However, during sepsis, the antioxidant capacity is insufficient, with decreased activities of superoxide dismutase (SOD) and catalase (CAT), as well as reduced GSH, leading to oxidative stress." (PMID 40520010, 2025). "Similarly, in the GP sepsis group, values for the studied antioxidants (SOD, CAT, and GSH) showed a downward trend on the second day, also without statistical significance." (PMID 39664147, 2024). "PEGylated catalase can effectively regulate the cytokine production by activated leukocytes, suppress the elevated level of AST, ALT, TNF-α, and IL-6 in mice with induced sepsis, and significantly improve the survival rate." (PMID 34888304, 2021). "Moreover, quercetin improves sepsis-induced acute lung injury in rats, by reducing lipid peroxidation and inflammation and increasing SOD and CAT levels." (PMID 32855764, 2020). "Furthermore, luteolin attenuates the sepsis-induced acute lung injury in mice by reducing lipid peroxidation and increasing SOD and CAT activity, in addition to suppressing the NF-κB pathway." (PMID 32855764, 2020). "The results showed that activity of SOD, CAT, and GSH was decreased obviously in sepsis mice." (PMID 29861657, 2018). "The results in this study show that animals with sepsis showed an increase in the superoxide dismutase (SOD) activity and a decrease in the catalase (CAT) activity, which resulted in an increase in SOD/CAT." (PMID 30524657, 2018). "Some research has revealed that SOD activity increased without a proportional increase in CAT activity during sepsis." (PMID 29230271, 2017). "Finally, the beneficial effects of Gallic acid pretreatment in sepsis are evident from the observations that Gallic acid partially restored SOD and catalase activity and completely reversed lipid peroxidation." (PMID 25018890, 2014). "Therefore, SOD2 plays a crucial protective role against oxidative damage; however, alteration in the SOD:CAT ratio, for example, an overexpression of SOD2, could lead to an increase in the levels of oxidative stress and morbidity in sepsis." (PMID 40725160, 2025). "Additionally, in a sepsis-induced cardiac injury model, monotropein significantly enhanced antioxidant defenses by increasing reduced glutathione levels (GSH), catalase (CAT) activity, and total antioxidant capacity, while reducing malondialdehyde (MDA) levels." (PMID 40941985, 2025). "In summary, we have demonstrated the PEGylated catalase can effectively regulate the production of cytokines by leukocytes, suppress the elevated level of AST, ALT, TNF-α, and IL-6 and mitigate the damage to the liver, kidney, lung function and other organs in mice with induced sepsis." (PMID 34888304, 2021).
Sepsis (continued). "Sepsis induction reduced NF-κB and SOD2 protein expression but increased their acetylation, and this was accompanied by an increase in proinflammatory cytokines (TNF-α/IL-6/IL-10) and oxidative stress (indicated by reduced SOD2 activity, GSH content, GSH/GSSG ratio, and CAT activity)." (PMID 33790896, 2021). "Using low-grade and midgrade models of sepsis in rats, this study found that the AChE and CAT activities in the diaphragm decreased, while the contents of TBARS and protein carbonyls, the activity of MPO and SOD, and the SOD/CAT ratios increased at 24 h after CLP surgery." (PMID 29230271, 2017). "Similarly, a study on sepsis revealed curcumin's ability to decrease serum inflammatory markers (IL-6, IL-18), oxidative stress indicator MDA, and increase antioxidants like Nrf2, catalase, and SOD, implicating its potential to target ferroptosis-related lipid peroxidation in clinical settings." (PMID 38519984, 2024).
ischemia (63 papers, 2011 to 2025). A hypoperfusion of the BLOOD through an organ or tissue caused by a PATHOLOGIC CONSTRICTION or obstruction of its BLOOD VESSELS, or an absence of BLOOD CIRCULATION. "Oxidative stress associated with ischemia/reperfusion injury is reduced by increases in the activities of antioxidant enzymes such as superoxide dismutase, catalase, and kidney glutathione peroxidase." (PMID 31067839, 2019). "In our study, we found that LYC at the doses of 2.5 and 5 mg/kg bw administrated 60 min before initiation of ischemia caused a substantial increasing in the I/R induced decrease in CAT." (PMID 24590927, 2015). "In addition, over-expression of SODs, glutathione peroxidase (GPx) and catalase (CAT) also act to protect against ischemia associated cytochrome c release from mitochondria, thereby limiting the occurrence of apoptotic cell death." (PMID 23976998, 2013). "CAT activity was significantly lower in the ischemia group compared to the control group (p < 0.001)." (PMID 40235540, 2025). "In conditions of induced myocardial infarction due to ischemia, pretreatment of rats with silymarin for 7 days prevented the reduction in the specific activity of CAT and SOD, which is in accordance with our results." (PMID 38675181, 2024). "A previous experiment has found that antioxidant enzymes including SOD-1, SOD-2, CAT, and GPx in kidneys exposed to ischemia for 30, 60, 90 min, 2 h, and 24 h are reduced significantly." (PMID 36790289, 2023). "Activation of KATP channels during ischemia also maintains at a high level the activity of enzymes of the antioxidant system catalase and superoxide dismutase, prevents mPTP opening, and suppresses apoptosis and necrosis of cardiomyocytes." (PMID 37265475, 2023). "SOD, GSH-Px and CAT are among the most important antioxidant enzymes, which confer protection against ischemia." (PMID 37303567, 2023). "Polymeric NP-mediated CAT delivery improved neuronal recovery from H2O2-induced oxidative stress and facilitated the recovery of neurons better than free CAT, suggesting possible applications in ischemia for ameliorating the level of irreversible brain injury." (PMID 38002010, 2023). "The expression in superoxide dismutase and catalase was significantly downregulated in ipsilateral torsional testes of testicular ischemia-reperfusion group compared with sham-operated control group (P < 0.001)." (PMID 35602096, 2022). "The study showed that the activities of SOD, GPx and CAT were significantly decreased after ischemia, which was significantly different from the control group (p < 0.01)." (PMID 35268655, 2022). "Another study employed a transgenic mouse overexpressing a mitochondrial-targeted catalase (scavenger of hydrogen peroxide), which was shown to decrease ischemia muscle injury and improve mitochondrial function in diet-induced diabetic mice." (PMID 33353218, 2020). "But, increase the dose to 50 and 100 mg/kg ameliorated ischemia-induced heart injury by increase of superoxide dismutase and catalase activity." (PMID 32641948, 2019). "Experimental studies showed that both the SOD and catalase activities are calcium - sensitive and changes in their activity would be expected to occur during ischemia, which can result in decreased antioxidant capacity of the bladder smooth muscle and mucosa." (PMID 30325606, 2018). "In myeloid cells, catalase over-expression reduced angiogenesis during hindlimb ischemia and prevented monocyte migration." (PMID 24853285, 2014). "CAT level results were recorded; 7.08 ± 0.609 in the sham group, 6.15 ± 0.119 in the Taurine group, 5.02 ± 0.62 in the ischemia group, and 5.36 ± 0.384 in the treatment group." (PMID 21418563, 2011). "Our previous studies indicate that either PEP-1-superoxide dismutase 1 (SOD1) or PEP-1-catalase (CAT) fusion proteins protects myocardium from ischemia-reperfusion-induced injury in rats." (PMID 21600015, 2011). "CAT activity was significantly lower in the IR group than in the ischemia group (p < 0.001)." (PMID 40235540, 2025).
ischemia (continued). "Lycopene reduces MDA and increases CAT in a rat model of hepatic ischemia and reperfusion." (PMID 40625633, 2025). "Modern organic donors, such as S-memantine and MTC, reduce Ca2+ excitotoxicity and GSH deficiency in ischemia, activate SOD, CAT, GPx, PI3K/AKT, and MEK-ERK, and inhibit apoptosis, endoplasmic reticulum stress, and TREK-1, demonstrating targeted mechanisms for neuronal regeneration." (PMID 41465271, 2025). "CAT activity was significantly lower in the IR group compared to the ischemia group (p < 0.001)." (PMID 40235540, 2025). "Furthermore, farboxyfullerene decreased the increase in lipid peroxidation products, decreased MDA levels, and increased superoxide dismutase, glutathione, and catalase levels depleted by ischemia in cerebral ischemia–reperfusion injury." (PMID 39202513, 2024). "Specifically, the predicted CaT abnormalities in the form of high and low peaks and irregular double peaks in the plateau phase were also observed experimentally in hiPSC-CMs in ischemia." (PMID 38516812, 2024). "Taken together, these studies indicate that the antioxidative capacity of HAM, particularly its ability to upregulate key antioxidant enzymes like SOD and CAT, plays a crucial role in alleviating oxidative stress and promoting myocardial survival after ischemia/reperfusion injury." (PMID 39519249, 2024). "Notably, the reverse mode of Na+/Ca2+ exchanger (NCX) was augmented (∼8%) in ischemia, which also contributes to CaT elevation, and this is in accord with the data reported for Langendorff-perfused mice hearts in ischemic conditions." (PMID 38516812, 2024). "The malondialdehyde content increased significantly, while superoxide dismutase and catalase protein expression and testicular spermatogenesis reduced significantly in ipsilateral testes of testicular ischemia-reperfusion group, as compared with sham-operated control group." (PMID 35602096, 2022). "LYC decreases MDA and increases CAT activity in a rat model of hepatic ischemia and reperfusion." (PMID 36431836, 2022). "The levels of malondialdehyde (MDA) and the activity of total-superoxide dismutase (T-SOD), glutathione peroxidase (GSH-Px), and catalase (CAT) in retinal tissues that had been altered by ischemia–reperfusion injury, recovered to normal after Diosmin administration." (PMID 35625813, 2022). "Cardiac mitochondria can degrade H2O2 via the glutathione (GSH), thioredoxin (TRX), and catalase pathways, and, therefore, altered activity of these pathways could explain the difference in ROS production between control and ischemia mitochondria." (PMID 35867709, 2022). "Consistent with our result, we previously used EC-specific catalase transgenic mice to demonstrate that EC-derived H2O2 plays an essential role in ischemia-induced arteriogenesis/angiogenesis, NFκB-dependent adhesion molecule expression and inflammatory cells recruitment." (PMID 26437801, 2015). "Finally, we injected catalase, an enzyme degrading hydrogen peroxide and hence counteraction effects of ROS after 2-hr ischemia but before 1-hr reperfusion." (PMID 26442853, 2015). "At the dose of 600 mg/kg, Berberis vulgaris significantly increased SOD levels compared to the ischemia group CAT activity was significantly higher in the BV300 and BV600 groups compared to the ischemia group." (PMID 40235540, 2025). "CAT activity was significantly higher in the BV300 and BV600 groups compared to the ischemia group (p > 0.99, p = 0.9997)." (PMID 40235540, 2025). "Simultaneously, ischemia inhibits the synthesis and activity of critical antioxidant enzymes, such as superoxide dismutase (SOD), catalase (CAT), and glutathione peroxidase (GSH-Px), thereby reducing the body’s ability to eliminate free radicals." (PMID 40421420, 2025). "MDA, SOD, GSH-Px and CAT levels in the rodent cerebral cortex, hippocampus and striatum post-MCAO ischemia were reported as secondary outcome measures in two included studies." (PMID 37303567, 2023).